EZH2 (enhancer of zeste 2 polycomb repressive complex 2 subunit)
Diseases named in the same sentence as EZH2 in open-access papers (continued):
Sharing a sentence is not in itself a finding about the gene and the disease.
cancer (continued). "This study reveals that inhibition of EZH2 activity may be a compelling therapeutics for a spectrum of cancers with genetic alterations conferring a proliferative dependency on EZH2 enzymatic activity despite EZH2 itself is not genetically changed in the cancers." (PMID 25520914, 2014). "As EZH2 is the catalytic subunit of polycomb repressive complex 2, which mediates epigenetic gene silencing by trimethylating histone H3 lysine 27, suppression of EZH2 by SAHA and DZNep may induce transcriptional activation of miR-1246, miR-302a and miR-4448 in cancer cells." (PMID 24861464, 2014). "Mechanistic studies showed that DZNep effectively depletes cellular levels of PRC2 components EZH2, SUZ12 and EED and inhibits histone H3K27 methylation suggesting a unique feature of DZNep as a novel chromatin remodeling compound that could be used as a novel cancer therapeutic." (PMID 21814622, 2011). "However, it appears that tolerance induction by the tumors expressing, STEAP or EZH2 may not be leaded, because we observed that cancer patient's PBMC could respond to the peptides and produced lymphokines." (PMID 22053850, 2011). "In addition, the protein levels of EZH2 was significantly up-regulated in PC3 PDGF-D cells relative to PC3 Neo cells and these results clearly suggest that the EMT-type characteristics of PC3 PDGF-D cells are consistent with the signatures of stem cells or cancer stem-like cells." (PMID 20805998, 2010). "We found that the expression of SPIN4, EZH2, and DNMT3A to be elevated in many human cancers compared to the corresponding non-malignant tissue samples." (PMID 41676612, 2026). "The compound DZNep was the first EZH2-targeting agent, known to reduce PRC2 complex protein levels, inhibit H3K27me3, and selectively induce apoptosis in cancer cells without affecting normal cells." (PMID 40959108, 2025). "In contrast, the expression of HLA class 1, which is critical for immune cell recognition of cancer cells, was slightly elevated only in the presence of IFN-γ, and was not affected by EZH2 inhibition." (PMID 40308579, 2025). "EZH2 inhibitors, such as Tazemetostat (EPZ-6438), GSK126, and CPI-1205, have been developed to treat EZH2 overexpressing cancers and non-oncological diseases." (PMID 37461108, 2023). "Although the epigenetic role of PRC2 is reported to be inhibited by the upregulated H3K4me3, the core components, EZH2 and SUZ12, have been shown to have oncogenic roles independent of PRC2 in several cancer types including NSCLC." (PMID 33916417, 2021). "Among the EZH2-inhibiting compounds, small molecule inhibitors of EZH2, GSK-126, PF-06821497, MAK683, CPI-0209, CPI-1205 and DS-3201 have entered into clinical trials, although none of these has been approved for cancer treatment, yet." (PMID 33761971, 2021). "Even though the direct link between EZH2 and EPCAM in cancer has not been reported, our results suggest a possible interaction of these two genes associated with somatic H3K4me3 signals in NSCLC." (PMID 33916417, 2021). "The major role of EZH2 in oncogenesis is known to engage in the proliferation and development rather than the EMT process of the cancer." (PMID 33291558, 2020). "The up-regulation of EZH2-silenced tumor suppressor genes, CDKN1C, DAB2IP, and WNT5a, was found in NSC745885-treated cancer cells, but not SV-HUC-1 cells." (PMID 32880874, 2020). "This phosphorylation was later found to enhance the enzymatic activity of EZH2 in regulating non-histone substrates, such as androgen receptor and STAT3, in different cancer types." (PMID 27494834, 2016). "We found that, despite not having representatives of their families, TLR7, BCL2, EZH2, and MDM2 for example, scored highly using the druggability models (74% or higher using the all-drug-target model; and 85% or higher using the cancer-drug-target model)." (PMID 26699810, 2015).
cancer (continued). "This point was confirmed by the weak anti-proliferation activity of the potent EZH2 inhibitor 5, showing that inhibition of H3K27 methylation alone was not sufficient to inhibit proliferation of these cancer cells." (PMID 25359765, 2014). "The oncogenic EZH2 is also identified as the therapeutic target of NSC745885, which has a highly selective toxicity towards cancer cells but not normal cells." (PMID 25431950, 2014). "Perhaps due to the parallel increase of MMSET and EZH2 in prostate and other tumors, studies to date have not shown a net increase in H3K36 or depression of H3K27me3 in advanced-stage cancers." (PMID 25188243, 2014). "It is worth noting that the relationship pattern between EZH2 and HIF‐1α is not unique in cancer." (PMID 38072662, 2024). "Given the canonical and non-canonical pleiotropic effects of EZH2, inhibition with HKMTI-1-005, either alone or as part of a combinatorial approach, may provide a benefit to the treatment of other cancers." (PMID 37035245, 2023). "However, the mechanism of action through which EZH2 targets and regulates RUNX3 expression and the resulting variations in various behaviors presented in cancer cell life activities have not been elucidated." (PMID 38048186, 2023). "Besides that, EZH2 also exhibited a positive or negative correlation with the MHC and immunostimulatory genes in pan-cancer." (PMID 36545914, 2023). "Disruption of EZH2-EED interaction also reduces the protein levels of EZH2 and may have broader therapeutic implications for PRC2-addicted cancers that are either dependent or independent of its HMT activity." (PMID 34617019, 2021). "We ruled out a central role for EZH2 methyltransferase activity in the refractoriness to SAHA in these cells, although the dependency on a non-catalytic role for EZH2 cannot be completely discounted, as it is known to affect the survival of the SWI/SNF-mutant cancer cells." (PMID 34262032, 2021). "Interestingly, the exchange of PRC2 subunit EZH2 and SWI/SNF ATPase subunits BRM and BRG1 was observed in CD4+ T cells restimulated and growing with cancer cells as compared to control without cancer cells." (PMID 34439305, 2021). "Moreover, the core components, EZH2 and SUZ12, have been reported to have oncogenic roles independent of PRC2 in several cancer types including NSCLC." (PMID 33916417, 2021). "Notably, activation of the PTEN, ES, AR-V, PRF and EZH2 pathways, a feature of NMF1 cancers, was not present in DESNT-non-NMF1 cancers." (PMID 32708551, 2020). "We showed that SNAI2 could recruit EZH2 but not SUZ12, suggesting SNAI1 and SNAI2 have different functions and non-overlapping roles in cancer cells and might cooperate to recruit PRC2 to the CDH1 promoter." (PMID 31938073, 2020). "However, to our knowledge, no studies targeted the common regulation of EZH2 and KDM6B during EMT and cancer." (PMID 34991274, 2018). "Since inactivation of both EZH2 and SETD2 leads to aberrant methylation at the respective histone H3 lysine residue, it is unclear why H3K27M and H3K36M are not as frequent as expected in these cancers." (PMID 30101054, 2018). "The results of chromatin immunoprecipitation experiments showed that both EZH2 and OGT are targeted to the promoter regions of FOXA1 and FOXC1 and knockdown of EZH2 or OGT affects expression of studied genes in breast non-malignant (MCF10A) and cancer cells (MCF7, T47D and MDA-MB-231)." (PMID 29864144, 2018). "Regarding the requirement of EZH2 for neural progenitor proliferation, our findings reveal notable differences in the observed mechanism by which PRC2 complex promotes proliferation in ESCc and cancer cells." (PMID 27248655, 2016). "Interestingly, CD133 depletion suppressed the expression of all of the core stemness genes and EZH2 in NTERA2 cells, while the expression of other cancer-related genes such as hTERT41, 42 and DAB21P43 was not affected." (PMID 26539911, 2015).
cancer (continued). "This suggests that the EZH2-MYC interactions may depend on the presence of specific co-factors or post-translational modifications that facilitate that interaction and are not present in healthy cells or in all types of cancers." (PMID 37664059, 2023). "The strikingly higher SFRP4 expression in ERG positive (>30% with strong SFRP4 positivity) than in ERG negative cancers (<15% with strong SFRP4 positivity) could be explained by the transcriptional activation of ERG and its direct target EZH2, known reported as the upstream regulator of SFRP4." (PMID 32677026, 2020). "The results from either array or RNA sequencing data supported the negative correlation between HBP1 and EZH2, whereas positive correlation between HBP1 and p21 also existed in cancers and suggested their potential roles in regulation of tumorigenesis for many cancer types." (PMID 27129219, 2016). "However, we found that no obvious difference of VASH1 or Ephrin-B2 expression was observed between EZH2-overexpressed and EZH2-silenced NPC cells (data not shown), suggesting that the alteration of VASH1 and Ephrin-B2 induced by EZH2 was cell type dependent in cancer cells." (PMID 25237831, 2014).
infection (68 papers, 2012 to 2026). The state of being infected such as from the introduction of a foreign agent such as serum, vaccine, antigenic substance or organism. "We found that the inhibition of EZH2 causes transcriptional activation of numerous immune genes and inhibits the subsequent infection by influenza A virus." (PMID 36768720, 2023). "The gain in function here is far greater than anticipated from the LPS responses, and the gain in cell numbers suggests a more profound change in macrophage behavior resulting from EZH2 loss, possibly extending to reduced cell death in response to infection." (PMID 34464475, 2021). "Acute pathogen infection models suggest that loss of Ezh2 selectively compromises SLEC or MPEC populations, depending upon the model, yet agree that the responding acute CD8+ T cell population exhibits reduced survival and altered cytokine production." (PMID 33117406, 2020). "As we introduced previously, EZH2-abalation affects the regulatory T cell generation, increased the risk of infection, and also dampen the immune response against cancerous cells." (PMID 27784285, 2016). "In contrast with our findings in vitro, there was little evidence of excess cytokine expression from the T cells of Ezh2-deficient mice after infection with toxoplasma or when they were transferred into Rag−/− host animals." (PMID 26090605, 2015). "We found that CD4-Cre; Ezh2fl/fl mice exhibited a significantly increased mortality rate compared with control animals, with the majority of the Ezh2-deficient animals dying in the second and third weeks post infection." (PMID 26090605, 2015). "Thus, loss of EZH2 in pulmonary macrophages greatly enhances their ability to restrict the systemic spread of a localized infection." (PMID 34464475, 2021). "As EZH2 has been implicated in responses to other infections, we examined if a single uropathogenic infection could alter expression of the critical epigenetic writer, EZH2, and the histone mark which it catalyzes, H3K27me3." (PMID 26964089, 2016). "The relative mRNA levels of Ezh2 and Suz12 showed different expression levels in the infection group." (PMID 38992966, 2025). "In vitro HAs infection with the high-risk HCMV-DB and GB strains resulted in a pro-oncogenic cellular environment with increased Myc and EZH2 expression, sustained growth of CEGBCs, and spheroid formation as well as invasion in 3D cultures." (PMID 38553638, 2024). "Here, we found that the infection of PRV significantly down-regulated the expression of EZH2 and that expression of EZH2 significantly promoted PRV proliferation." (PMID 39689152, 2024). "NDV viral growth curves showed similar results, with significantly higher and lower viral titers at 12–24 h post-infection after circ-EZH2 knockdown and overexpression, respectively." (PMID 37065234, 2023). "Genomic DNA was isolated from TFH cells sorted from the spleen of control and Ezh2-/- mice at day 8 after infection." (PMID 36045674, 2022). "EZH2‐targeted mice were assessed 40 hours after infection; they were killed at this time point due to the severity of disease." (PMID 34464475, 2021). "The histone H3K27 methyltransferases EZH2 is particularly interesting since its inhibitors seem capable to suppress infection with DNA and RNA viruses according to Arbuckle and colleagues." (PMID 34198800, 2021). "On day 2 after infection, we compared EZH2 expression and H3K27me3 modification between naïve (CD44loCD25−), TH1 (CD25hiCXCR5−) and TFH (CD25loCXCR5+) SMARTA cells." (PMID 30842630, 2020). "By using an acute lymphocytic choriomeningitis virus (LCMV) infection model, we observed elevated expression of EZH2 in early-activated virus-specific CD4 T cells." (PMID 32999031, 2020). "After reconstitution, these chimeric mice were initially infected with the LCMV Armstrong strain and then administered tamoxifen from days 4 to 7 after infection to induce the deletion of EZH2." (PMID 30842630, 2020).
infection (continued). "Next, we analyzed the kinetics of EZH2 expression in TFH SMARTA cells at different time points after infection and found that virus-specific TFH cells rapidly increased EZH2 expression upon infection and reached a peak on day 2 postinfection." (PMID 30842630, 2020). "From infection models, differentiation, effector function, survival, and memory recall are few of the processes affected by modulating EZH2 activity, with some effects being pathogen dependent." (PMID 33117406, 2020). "On day 2 after infection, we visualized the efficient deletion of EZH2 expression in Ezh2fl/fl SM cells overexpressing iCre." (PMID 30842630, 2020). "On day 2 after infection, we validated the efficiency of Ezh2 deletion in Ezh2fl/fl SM-Cre cells and observed a remarkable reduction in the TFH cell commitment of the Ezh2fl/fl SM-Cre cells compared to Ezh2+/+ SM-Cre cells." (PMID 30842630, 2020). "On day 5 after LM-GP66 infection, the transferred virus-specific CD4 T cells with tamoxifen-induced EZH2 deficiency were barely detectable, while vehicle-treated mice showed a robust memory CD4 T cell response upon infection." (PMID 32999031, 2020). "We next determined the role of EZH2 in the late differentiation of TFH cells during an acute infection." (PMID 30842630, 2020). "During TFH differentiation, EZH2 expression spikes within 2 days after infection and then decreases to the baseline level that is comparable to naive CD4+ T cells." (PMID 30842630, 2020). "The loss of c-Src protein was complete at 96 h post-infection, correlating with an increased AMP:ATP ratio, AMPK activation, mTORC1 suppression, and reduced Ezh2 and Suz12 protein expression." (PMID 31263101, 2019). "To further validate that EZH2T416 phosphorylation is responsible for inhibiting ERα expression in TNBCs, we stably expressed phospho-mimic EZH2 (myc-EZH2T416D) in BT 549 cells by lentiviral infection." (PMID 31704972, 2019). "The protein level of EZH2 was enhanced in p-SLC34A2 group, while si-HIF-1α infection resulted in EZH2 expression significantly declined in p-SLC34A2 group." (PMID 30038060, 2019). "Similar results were observed at 60 h post-infection, when both WT and Ezh2–/– Smarta CD4+ T cells were in 4th and 5th divisions." (PMID 30575739, 2018). "Both Arf and Ink4a transcripts were highly induced in Ezh2–/– Smarta TFH cells in the adoptive transfer/LCMV-Arm infection model." (PMID 30575739, 2018). "On day 8 post-infection (8 dpi), both wild-type and Ezh2–/– CD4+ T cells were activated at similar frequency, but fewer activated CD4+ T cells were detected in Ezh2–/– mice." (PMID 30575739, 2018). "During the latent state, growth of EZH2-knockout (KO) cells was significantly slower after infection compared to wild-type controls, despite similar levels of viral gene expression between cell lines." (PMID 30487153, 2018). "At 60 h post-infection, Ezh2–/– Smarta CD4+ T cells were detected in recipient spleens in similar numbers as WT cells, and showed similar rate of Caspase-3/7 activation." (PMID 30575739, 2018). "Deleting p19Arf alone did not exhibit detectably impact on TFH cells elicited by the LCMV-Arm infection, and ablating p19Arf in Ezh2–/– cells rectified the frequency of CXCR5+SLAMlo TFH cells and partially restored TFH cell numbers on 4 dpi." (PMID 30575739, 2018). "The expression level of EZH2 increased upon infection of primary B cells by EBV, suggesting its importance in virus function." (PMID 30487153, 2018). "For clarity, only flow data from the infection conditions used with cells expressing scrambled and EZH2 shRNAs are shown." (PMID 28246360, 2017). "As compared to WT CD8+ T cells, Ezh2−/− CD8+ T cells produced 1.5- to 2-fold more OVA257–264-specific T cells 3 days after infection, maintained at 4 days, and dramatically declined by 5 days." (PMID 29242551, 2017).